VCAM1 (vascular cell adhesion molecule 1)
Diseases named in the same sentence as VCAM1 in open-access papers (continued):
Sharing a sentence is not in itself a finding about the gene and the disease.
breast cancer (continued). "Another report shows that VCAM-1 enhances lung metastasis of breast cancer cells by triggering AKT activation in cancer cells which protects cells from TRAIL-induced apoptosis." (PMID 27329720, 2016). "Surprisingly, VCAM-1 facilitated lung colonization through providing survival signaling to breast cancer cells." (PMID 26592552, 2015). "We further demonstrated that VCAM-1 has a growth-promoting role in tumorigenesis in vivo, and furthermore promotes breast cancer migration and affects EMT mediated by TGF-β1 and IL-6." (PMID 24583847, 2014). "Pretreatment with VCAM-1 antibody reduces breast cancer cell migration and bone metastasis, indicating that VCAM-1 plays a critical role in tumor migration; its disruption can prevent bone metastasis." (PMID 25277191, 2014). "Breast cancer cells expressing the leukocyte receptor VCAM-1 can thrive in leukocyte-rich microenvironments through juxtacrine activation of a VCAM-1–Ezrin-PI3K/Akt survival pathway." (PMID 24886617, 2014). "In the present study, we observed that VCAM-1 expression can be induced in many breast cancer epithelial cells by cytokine stimulation in vitro and its up-regulation directly correlated with advanced clinical breast cancer stage." (PMID 24583847, 2014). "Our findings uncover the possible mechanism of VCAM-1 activation facilitating breast cancer progression, and suggest that targeting VCAM-1 is an attractive strategy for therapeutic intervention." (PMID 24583847, 2014). "In breast cancer, VCAM-1 is a crucial activator of indolent bone metastasis and osteoclast recruitment to form bone lesions." (PMID 25277191, 2014). "VCAM-1 is aberrantly expressed in breast cancer cells and mediates pro-metastatic tumor-stroma interactions." (PMID 24829073, 2014). "In this study, we first observed the increasing expression of VCAM-1 in breast cancer cells after inflammatory cytokine treatments." (PMID 24583847, 2014). "As VCAM1 is a known ligand of VLA-4 and is involved in breast cancer metastasis, we hypothesized that VCAM1 contributes to tumor cell–T cell interactions." (PMID 40955669, 2025). "Initially characterized in 1989 for its vital role in mediating cell adhesion in melanoma, vascular cell adhesion molecule (VCAM)-1 has garnered significant attention as a crucial factor for the development and progression of solid tumors, particularly breast cancer and GC." (PMID 40927361, 2025). "Notably, upregulated VCAM1 expression was observed in primary breast cancer of Black patients along with a higher frequency of heterotypic CTC-WBC clusters than White patients." (PMID 40955669, 2025). "Abnormal VCAM-1 expression promotes lung and bone metastases in breast cancer." (PMID 40927361, 2025). "HMFe@BS is camouflaged with MΦM (MΦM@HMFe@BS) to evade macrophage-phagocytosis, increase blood circulation time, and accumulate within the breast cancer through the interaction between α4-integrin in MΦM and breast cancer overexpressed vascular cell-adhesion molecule (VCAM)-1." (PMID 40225567, 2025). "In silico analysis confirmed higher numbers of tumour-infiltrating lymphocytes in basal breast cancers and that higher numbers were significantly associated with endothelial cell activation molecules, co-clustering with upregulated ICAM-1 and VCAM-1 amongst others." (PMID 39792888, 2025). "Macrophages cells (RAW264.7) can bind to cancer cells through their high expression of integrins α4 and β1, and cancer cell with high expression of vascular cell adhesion molecule-1 (VCAM-1), thus promoting macrophage targeting in breast cancer lung metastasis." (PMID 38610015, 2024). "Next, we focused on the protein expression levels of Itgav, Itgb3, and Vcam1, as they exhibited a progressive increase during mouse cSCC progression and had previously been associated with different EMT transition states in EpCAM− skin and breast cancer cells." (PMID 39075581, 2024).
breast cancer (continued). "VCAM-1 is highly expressed in murine 4T1 breast cancer cells, therefore, in vivo, macrophage membranes retaining integrin α4β1 enable liposomes to target metastatic cells and produce a notable inhibitory effect on lung metastasis of breast cancer." (PMID 36768966, 2023). "VCAM-1 expression has been described in several types of cancer including breast cancer." (PMID 37773178, 2023). "In addition, neutralizing VCAM-1 antibodies inhibit neutrophil and cancer cell infiltration and metastasis in in vivo models of breast cancer." (PMID 37773178, 2023). "Other reports demonstrate that serum VCAM-1 concentration correlates with the micro-vessel density of breast cancer and may be a substitutive marker of angiogenesis." (PMID 36979820, 2023). "The downregulation of VCAM1 expression blocks breast cancer cell metastasis." (PMID 37511481, 2023). "The AuNDs were coated with RAW 264.7 macrophage membranes to enable targeted delivery to MDA-MB-231 human breast cancer cells via the active binding of macrophage-expressed α4 integrins to overexpressed vascular cell adhesion molecule-1 (VCAM-1) on MDA-MB-231 s." (PMID 35960404, 2022). "Interestingly, e-cigarettes also promote breast cancer cell growth and metastatic lung colonization, mediated by cross-talk with tumor-associated macrophages via CCL5 and VCAM-1 pathways in an animal study." (PMID 35406378, 2022). "In addition, in the study of breast cancer, the direct role of VCAM1 in tumor metastasis was also confirmed." (PMID 36482940, 2022). "Therefore, AREG+, IL7R+ and VCAM1+ innate lymphoid cells can help determine prognosis for breast cancer patients." (PMID 36497286, 2022). "In the process of lung metastasis of breast cancer, the interaction between α4 integrin of macrophages and the vascular cell adhesion molecule-1 (VCAM-1) of cancer cells accelerates the survival of metastatic cells and triggers the generation of metastatic lesions." (PMID 34099630, 2021). "A recent study identified neutrophils accompanying CTCs in patients with advanced-stage breast cancer where interactions between neutrophils and CTCs mediated by VCAM1, promoted cell cycle progression and metastatic seeding, opening up new therapeutic vulnerabilities to prevent breast cancer spread." (PMID 34026650, 2021). "The interaction between malignant T cells and immune cells may possess similar effects like VCAM1-mediated mechanisms in breast cancer cells." (PMID 33816243, 2021). "Moreover, VCAM‐1 overexpression in breast cancer promotes bone metastasis by activating osteoclastogenesis and subsequent early relapse." (PMID 34427969, 2021). "Therefore, the depletion of VCAM-1 expression is potentially important for the prevention of cancer growth and is considered as an important therapeutic target in breast cancer." (PMID 32751068, 2020). "Thus, upon α4-integrin engagement on monocytes, VCAM-1 delivers anti-apoptotic signals into breast cancer cells through the PI3K/Akt pathway favoring tumor cell survival." (PMID 31447834, 2019). "Breast cancer metastasis to the bone may be promoted by NF-κB-mediated aberrant expression of vascular cell adhesion molecule 1 (VCAM-1)." (PMID 31817646, 2019). "Overexpression of VCAM1 has been shown to confer cisplatin resistance in breast cancer cells." (PMID 31684899, 2019). "Activation of VCAM1 has been reported in lung secondary masses from breast cancer." (PMID 31330946, 2019). "Importantly, MMP1 and VCAM1 expression in part constitute a profile of invasive breast cancer cells." (PMID 29735912, 2018). "Also of note was the significant decrease in VCAM1 (2.6-fold), TBS2 (5.2-fold), MMP1 (7.7-fold), COL14A1 (2-fold), and MMP13 (3.3-fold), all of which have been associated with breast cancer cell invasion and metastasis to bone, lung, and/or the lymphatics." (PMID 29735912, 2018).
breast cancer (continued). "However, Lu and co-workers characterized a bone metastasis dormancy model of breast cancer and showed that the expression of vascular cell adhesion molecule 1 (VCAM-1) was in part mediated by NF-κB pathway." (PMID 30456206, 2018). "A similar mechanism of OC-mediated escape from dormancy has been reported in breast-cancer cells that aberrantly express the vascular cell-adhesion molecule 1 (VCAM-1), recruit α4β1 OC precursors by engaging in VCAM-1/α4β1 binding to increase Oct activity, and stimulate tumor growth." (PMID 29461491, 2018). "Specifically, this may occur through the release by both types of cells of growth factors and cytokines, such as SDF-1, TGF-β1 and BMPs, and over-expression of HIF-1α, NF-κB, vascular cell adhesion molecule-1 (VCAM-1) and Notch in breast cancer cells." (PMID 29099748, 2017). "The serum VCAM-1 levels were also found to have prognostic significance in breast cancer patients." (PMID 26881177, 2016). "Also, breast cancer cell leucocyte receptor, vascular cell adhesion molecule 1 (VCAM1) binding to TAM α4-integrin explains the increased survival of VCAM1+ tumor cells in leucocyte-rich environments." (PMID 26243145, 2015). "Vcam1 is a pro-inflammatory molecule and facilitates breast cancer progression." (PMID 26512722, 2015). "The identification of pathways and target genes regulated by VCAM-1 that promote breast cancer progression and chemoresistance could be the key to new therapies for combating breast cancer." (PMID 24583847, 2014). "Likewise, VCAM-1 has been indicated to regulate tumor progression and bone metastasis in glioblastoma and breast cancer." (PMID 25277191, 2014). "Given previous reports indicating VCAM-1 of circulating cancer cells transmitting survival signals in breast cancer cells invading the lung, the integrin α4 on MφNPs could potentially interact with VCAM-1 of circulating cancer cells, aiding their migration into the metastatic site." (PMID 38111068, 2023). "Vascular cell adhesion molecule-1 (VCAM-1) is a transmembrane molecule that mediates the adhesion of immune cells to the vascular endothelium during inflammation and is related to the development of malignant neoplasms, such as breast cancer, melanoma, and renal clear cell carcinoma." (PMID 36979820, 2023). "They investigated whether MRI enhanced with the targeted anti-VCAM-1 microparticles of iron oxide (anti-VCAM-1 MPIO) would be able to depict up-regulated VCAM-1 in a model of human breast carcinoma cerebral metastasis in mice and if early detection of these metastases would be feasible." (PMID 24387195, 2014). "Monocytic cells carrying the α4-integrin receptor can bind to vascular cell adhesion molecule-1 (VCAM-1), highly expressed on the surface of mouse and human breast cancer metastatic cells in the lungs." (PMID 40427136, 2025). "As proof of concept, targeting VLA-4 (α4) disrupts the VCAM1–VLA-4 interactions between CTC and immunosuppressive DPT and inhibits metastasis, ultimately improving breast cancer outcomes." (PMID 40955669, 2025). "In contrast, VSMCs were treated with BC-CM from RGS5 knockdown breast cancer cells reversed the upregulation of TNF-α, VCAM-1 and macrophages adhesion." (PMID 37986113, 2023). "Further, tumor cells selected by brain endothelium adhesion expressed higher levels of MUC1, VCAM1, and VLA-4, which were relevant to breast cancer brain metastasis." (PMID 37108248, 2023). "This study also revealed that MMP1, VCAM1, FZD3, VEGFC, FOXM1 and MUC1 genes can be considered as markers of breast cancer occurrence because these genes show significant differential expression in breast neoplasms compared to normal tissue." (PMID 37958607, 2023). "Intracerebral xenograft rat models of MDA231Br-GFP (breast cancer) brain metastasis and U87MG (glioblastoma) were used to histologically examine the tumor-brain interface and to test the efficacy of VCAM-1–targeted MRI in detecting this region." (PMID 35312755, 2022).
breast cancer (continued). "RNA-sequencing data analysis on the human breast cancer cell line MDA-MB-231 has shown that CXCR4, PLLP, VCAM1, SLC7A11, SLC8A2, and TNFSF4 genes are highly over-expressed in brain metastasis." (PMID 35045088, 2022). "A previous study has shown that lung metastatic breast cancer cells aberrantly expressed ICAM-1- and VCAM-1-promoted metastatic cells for survival in the parenchyma microenvironment of lung." (PMID 34760697, 2021). "Stimulation with recombinant human IL-8 increased mucin-1 in MCF-7 and T47D breast cancer cells and decreased intercellular adhesion molecule 1 (ICAM-1) as well as vascular cell adhesion molecule 1 (VCAM-1) in T47D cells." (PMID 33809315, 2021). "Recent evidence suggests that VCAM1 interacts with VLA4 on endothelial cells, which mediates tumor cell adhesion, vascular extravasation, and brain metastases formation in breast cancer and induces the formation of an inflammatory environment." (PMID 32793471, 2020). "In this article, we investigated anti-VCAM-1 ssDNA aptamer and anti-IL4Rα RNA aptamer, conjugated to SPIO nanoparticles, for the diagnosis and treatment of breast cancer cells." (PMID 32751068, 2020). "In addition to endothelial cells, in cancer cells, knockdown of VCAM-1 in MDA231 breast cancer cells inhibited lung metastasis by reducing the adhesion to U937 leukocytes, the binding of VCAM-1 to α4β1 integrin might be responsible for tumor angiogenesis and metastasis." (PMID 32344794, 2020). "Upon binding of VCAM-1 of cancer cells, it activated PI3K/AKT signaling through the cytoplasmic peripheral protein Ezrin, leading to protection of the migrated breast cancer cells from potential cell death in the lungs." (PMID 32283687, 2020). "VCAM1, an endothelial cell adhesion molecule, upregulates PI3K-AKT signaling in breast cancer cells, as observed during lung metastasis." (PMID 27486983, 2016). "It is reported that serum levels of two important adhesion molecules, ICAM1 and VCAM1 are significant higher in patients with colorectal cancer, ovarian cancer, NSCLC and breast cancer." (PMID 26239324, 2015). "In addition, we also discovered that VCAM-1 activation was involved in the development of chemoresistance in NMuMG breast cancer cells after exposure to low-dose doxorubicin in vitro, and VCAM-1 may contribute to the activation of CD44 and ABCG2 pathways in NMuMG and MDAMB231 cells." (PMID 24583847, 2014). "We analyzed the mass spectrometry proteomic datasets of treatment-naive human breast primary tumors (n = 122) and found a higher expression of the VCAM1 protein in Black patients with breast cancer versus non-Black patients." (PMID 40955669, 2025). "In contrast, lapatinib, another TKI used to treat advanced HER2-positive breast cancer without causing HTN as a side effect, showed an insignificant effect on EC viability and the levels of LEENE, eNOS, and VCAM1 RNA in vitro and ex vivo." (PMID 37218991, 2023). "MCF7 breast cancer cells that do not express VCAM1 were transfected with a VCAM1 overexpression vector, and ectopic expression was confirmed by Western blotting and immunofluorescence imaging." (PMID 37085481, 2023). "The effect of VCAM-1 (vascular cell adhesion molecule 1) was inhibited, reducing the proliferation of MCF7 cancer cells, as well as reducing the number of paracrine endothelial cells in the same breast cancer model in vitro." (PMID 35269947, 2022). "Disseminated breast cancer cells residing in bone marrow perivascular niche are protected from chemotherapy by their integrin-mediated interactions with molecules including von Willebrand Factor (VWF) and vascular cell adhesion molecule-1 (VCAM-1)." (PMID 35994202, 2022). "VCAM-1 expression mediates adhesion of melanoma cells to LECs in vitro, but this was not the case for breast cancer cells, and there is no animal or clinical data supporting a role of VCAM-1 in tumor cell-LEC adhesion in vivo." (PMID 34685565, 2021).
breast cancer (continued). "The elevated expression of ANXA2 can contribute to the tumor progression in estrogen receptor (ER) negative breast cancer cell lines; pancreatic tumor progression can be inhibited by blocking VCAM1." (PMID 33287876, 2020). "We could furthermore identify, that these mesenchymal transformed breast cancer cells revealed a high ITGαV (CD51) and VCAM-1 (CD106) co-expression compared to non- invasive MCF-7 breast cancer cells." (PMID 33087801, 2020). "In addition, vascular cell adhesion molecule-1 (VCAM-1) expression was decreased, consequently lowering the potential for an extravasation of breast cancer cells." (PMID 32397337, 2020). "Interestingly, VCAM-1 has been shown to regulate breast cancer dormancy, while OPG can regulate the survival of breast cancer cells." (PMID 30990165, 2019). "Furthermore, previous studies showed that IL-23 increased the abundances of intercellular adhesion molecule-1 and vascular cell adhesion molecule-1 on endothelial cells, and improved the endothelial marker CD31 in mammary cancer." (PMID 30483821, 2019). "In addition, SDF-1α binds to CXCR7, another chemokine receptor that is highly expressed on breast cancer cells, and enhances CXCR7-mediated tumor migration and metastasis by activating STAT3, MMP9, MMP2 and VCAM-1." (PMID 31219799, 2019). "For example, high levels of soluble intercellular adhesion molecule 1 (ICAM-1), VCAM-1 and platelet-derived growth factor (PDGF) detectable in the BM plasma of untreated advanced breast cancer patients possibly contribute to DTCs escape out of the blood vessels into the BM." (PMID 31338489, 2019). "A recent study further supports a potential role of MMP2 in breast-to-brain metastasis, as it was found to belong to 5-gene expression signature (together with CXCL12, MMP11, VCAM1, MME) discriminating between primary breast cancer and breast cancer brain metastases." (PMID 29312881, 2017). "In addition, CXCR7 regulated breast cancer metastasis by enhancing expression of metalloproteinases (MMP-9, MMP-2) and vascular cell-adhesion molecule-1 (VCAM-1)." (PMID 24886617, 2014). "Additional studies have compared the expression of other adhesion molecules in radioresistant and radiosensitive breast cancer cell lines and found that the resistant cancer cells have increased expression of intercellular adhesion molecule-1 (ICAM-1) and vascular cell adhesion molecule-1 (VCAM-1)." (PMID 35992826, 2022). "Recent studies in breast cancer cells have revealed that CXCR7 activation by SDF‐1 increases components regulating cell adhesion and cell–matrix interaction, such as vascular adhesion molecule VCAM‐1 and matrix metalloproteinases MMP‐2 and MMP‐9, and SDF‐1 also promoted MMP‐9 expression in OC cells." (PMID 30051594, 2018).